TAAR1 (trace amine associated receptor 1)
Diseases named in the same sentence as TAAR1 in open-access papers (continued):
Sharing a sentence is not in itself a finding about the gene and the disease.
schizophrenia (continued). "Ulotaront (SEP-363856), which is currently in Phase III clinical development, was the first TAAR1 agonist to demonstrate efficacy in a randomized, double-blind, placebo-controlled Phase II clinical trial in patients with an acute exacerbation of schizophrenia." (PMID 38110609, 2024). "TAAR1 agonism has been proposed as a new treatment strategy for schizophrenia and related neuropsychiatric disorders." (PMID 38110609, 2024). "Recently, an association between mutations in the TAAR1 gene and schizophrenia was reported, suggesting the implication of TAAR1 in the pathways driving schizophrenia." (PMID 38675561, 2024). "Promising efficacy and safety results in patients with schizophrenia were reported for ulotaront, a TAAR1 agonist with additional 5-HT1A agonist activity, currently in Phase 3 clinical development [1,]." (PMID 38237896, 2024). "The most frequently studied receptor TAAR1 has already been investigated in the treatment of schizophrenia, demonstrating antidepressant and anxiolytic properties." (PMID 38927470, 2024). "TAAR1 has emerged as a promising target for the treatment of neuropsychiatric disorders, and the pharmaceutical industry initially focused on schizophrenia." (PMID 39110804, 2024). "Here we assessed the impact of ulotaront (SEP-363856), a TAAR1 agonist in Phase III clinical development for schizophrenia, on glutamate function in the mouse striatum and hippocampus." (PMID 38110609, 2024). "The TAAR1 agonist 50B significantly improved the positive symptoms of schizophrenia induced by MK801 in mice." (PMID 37153799, 2023). "The results stated previously suggested that as a novel agonist of TAAR1, 50B flowed to brain and had a role in the anti-positive symptoms of schizophrenia." (PMID 37153799, 2023). "SEP-363856, a novel therapy approved by the Food and Drug Administration for the treatment of schizophrenia, is a TAAR1 agonist in phase III clinical development." (PMID 36983018, 2023). "Ulotaront is the first TAAR1 agonist that has progressed to Phase 3 clinical trials for the treatment of schizophrenia." (PMID 37165101, 2023). "Although evidence exists for the therapeutic effects of 5-HT1A agonists in depression and anxiety-related disorders, the potential for efficacy of 5-HT1A agonists in schizophrenia, particularly in combination with TAAR1 agonism, remains to be explored." (PMID 37165101, 2023). "The ability of TAAR1 to modulate dopaminergic circuits has attracted considerable interest in the context of schizophrenia and psychosis in general." (PMID 37165101, 2023). "Based on current data, ulotaront shows potential to be a first-in-class TAAR1 agonist for the treatment of schizophrenia with a safety and efficacy profile distinct from current antipsychotics." (PMID 37165101, 2023). "TAAR1 primarily was shown outside the olfactory system, and this receptor has already been identified as the target of therapeutic agents for schizophrenia, depression, and drug addiction." (PMID 38002300, 2023). "Ulotaront is the first TAAR1 agonist for which phase 2 clinical trials have been completed and demonstrates efficacy in the treatment of patients with schizophrenia." (PMID 37509616, 2023). "TAAR1 is being studied as a potential therapeutic target in the treatment of various mental disorders, such as schizophrenia." (PMID 36976665, 2023). "It has been found that TAAR1 is an important regulator of DA and the 5-HT system and is considered to be a significant target for the treatment of schizophrenia." (PMID 35458749, 2022). "In particular, TAAR1 agonists have generated interest as potential treatments for schizophrenia and other psychoses due to TAAR1-mediated regulation of dopaminergic circuitry." (PMID 35484370, 2022). "In fact, the first drug based on TAAR1 agonism has successfully passed Phase II of clinical trials for the treatment of schizophrenia." (PMID 35625001, 2022).
schizophrenia (continued). "Uloturant, a trace amine-associated receptor 1 (TAAR1) agonist, is currently in Phase 3 clinical trials for schizophrenia." (PMID 35836971, 2022). "Ulotaront (SEP-363856) is a TAAR1 agonist with 5-HT1A agonist activity currently in clinical development for the treatment of schizophrenia." (PMID 35484370, 2022). "Further preclinical studies are necessary to evaluate efficacy, safety and tolerability of this potent TAAR1 agonist for the potential development of this compound as a new pharmacotherapy option for schizophrenia and other psychiatric disorders." (PMID 36359001, 2022). "TAAR1-based therapies have a strong potential in the treatment of several human disorders such as schizophrenia, addiction, depression, diabetes, and obesity." (PMID 35625001, 2022). "TAAR1 agonism is emerging as a principally new treatment option for a number of mental conditions, including schizophrenia." (PMID 36359001, 2022). "While initially suggested as an animal model of schizophrenia, TAAR1 knockout (KO) mice demonstrate not only enhanced responses to amphetamine and deficit in sensorimotor gating, but also show increased impulsivity and altered wake-sleep cycle." (PMID 36430544, 2022). "Particularly, it was found that TAAR1 agonists can counteract aberrant behavioral manifestations in various animal models relevant to schizophrenia, including hyperdopaminergic dopamine transporter knockout (DAT-KO) rodents." (PMID 36232878, 2022). "Based on elevated dopamine transmission, supersensitivity of D2 dopamine receptors and enhanced responsiveness to amphetamine, TAAR1-KO mice were proposed as a model of schizophrenia." (PMID 35625001, 2022). "SEP-363856 is a trace amine-associated receptor 1 (TAAR1) and 5-hydroxytryptamine type 1A (5-HT1A) agonist, currently in Phase 3 clinical trials for the treatment of schizophrenia." (PMID 33879769, 2021). "In the foreseeable future, findings from ongoing clinical trials with ralmitaront and ulotaront will be fundamental to elucidate the therapeutic utility of TAAR1 agonists, which hold great promise as a new drug class for the treatment of schizophrenia." (PMID 34947997, 2021). "In particular, agonist compounds have generated interest as potential treatments for schizophrenia and other psychoses due to TAAR1-mediated regulation of dopaminergic tone." (PMID 34947997, 2021). "Ulotaront, a trace amine-associated receptor 1 (TAAR1) and serotonin 5-HT1A receptors agonist, has demonstrated efficacy in the treatment of patients with an acute exacerbation of schizophrenia in a 4-week, double-blind, placebo-controlled study." (PMID 34887427, 2021). "In view of these new developments, we review TAAR1 pharmacology, candidate ligands in clinical development and the rationale for TAAR1 as a promising therapeutic target for neuropsychiatric disorders, focusing on schizophrenia." (PMID 34947997, 2021). "Preclinical data suggest TAAR1 agonists may be uniquely positioned to target the presynaptic mechanisms underlying dopamine synthesis capacity dysfunction in psychosis and modulate glutamatergic circuit alterations associated with core symptoms of schizophrenia." (PMID 34947997, 2021). "Foundational preclinical research and recent clinical evidence demonstrate the promise of TAAR1 agonists to be the first novel drug class for the treatment of schizophrenia in almost 70 years." (PMID 34947997, 2021). "In conclusion, in this open-label extension study, ulotaront, one of the first of a new class of TAAR1 agonists, in the daily dose range of 25–75 mg, was generally safe, well-tolerated, and effective in the long-term treatment of patients with schizophrenia." (PMID 34887427, 2021). "In the CNS, TAAR1 acts as a regulator of dopaminergic, glutamatergic, and serotonergic neurotransmission and is a novel therapeutic target for schizophrenia, depression, and addiction." (PMID 34946184, 2021).
schizophrenia (continued). "On the other hand, an exaggerated response to the dopaminergic stimulant amphetamine was observed in TAAR1-KO mice, both in terms of hyperlocomotor activity and striatal dopamine release, indicative of a schizophrenia-like dopamine phenotype." (PMID 34947997, 2021). "Particularly the ability of TAAR1 to regulate dopaminergic tone has been of interest in the context of schizophrenia and psychosis in general." (PMID 34947997, 2021). "In a series of recent studies, TAAR1 agonists demonstrated antipsychotic activity in the animal models of schizophrenia." (PMID 30233365, 2018). "This interest has largely focused on the most well-characterized family member, TAAR1, and its potential as a novel target for pharmacotherapy of psychiatric disorders, in particular schizophrenia and drug abuse, and more recently metabolic disorders." (PMID 30013475, 2018). "These and other observations strongly support the potential of TAAR1 agonists as a novel treatment approach for a range of dopamine-related disorders such as schizophrenia, ADHD, and addiction." (PMID 29977204, 2018). "Sunovion Pharmaceuticals Inc. also initiated a clinical study for SEP-363856, a dual agonist at 5-HT1A receptors and TAAR1, to treat schizophrenia." (PMID 29636691, 2018). "To date, TAAR1 has been demonstrated to be involved in a broad range of neuropsychiatric disorders including schizophrenia, depression, bipolar disorder, Parkinson's disease, sleep disorders, drug abuse and addiction." (PMID 29636691, 2018). "With regards to dopaminergic system related potential therapeutic utility, TAAR1 agonists have demonstrated activity in animal models pertinent to schizophrenia and addiction." (PMID 29977204, 2018). "Subsequently, Taar1 was considered as a drug target for treatment of alcohol and drug addiction, as well as Parkinson’s disease and schizophrenia." (PMID 29615904, 2018). "Whether this mechanism follows a positive dose–response relationship remains unclear; however, our study provides evidence supporting the potential role of the TAAR1 agonist ulotaront, especially at the already tested 100 mg dose in treating schizophrenia." (PMID 40795331, 2025). "In addition, the modulation of the dopaminergic system and the ability to reduce ventral tegmental area (VTA) firing and dopaminergic release led to experimenting with TAAR1 agonists as a potential treatment in schizophrenia and psychotic disorders." (PMID 39857669, 2025). "However, TAAR1 functional regulation of glutamate systems in schizophrenia-relevant brain areas such as striatum and hippocampus has been largely unexplored." (PMID 38110609, 2024). "TAAR1 has garnered substantial clinical interest over the last decade as a potential therapeutic target for several neuropsychiatric disorders, particularly schizophrenia." (PMID 39110804, 2024). "Here TAAR1 function is critical as TAAR1 knockout (TAAR1-KO) mouse models broadly display typical schizophrenia-like symptoms including hyperdopaminergia, behavioural hypersensitivity, predisposition to substance addiction, impaired cognition and disrupted locomotive functioning." (PMID 39553890, 2024). "TAAR1 agonists may be less efficacious than dopamine D2 receptor blocking drugs licensed for schizophrenia, yet the results are inconclusive." (PMID 39036710, 2024). "Furthermore, an understanding of unappreciated signalling mechanisms (Gq, Gs/Gq) by TAAR1 agonists has come to light with the discovery of selective compounds to treat schizophrenia-like phenotypes." (PMID 39553890, 2024). "Evidence from both human and animal studies suggested that current TAAR1 agonists may offer smaller benefits in improving symptoms of psychosis compared to dopamine D2 receptor blocking drugs already licensed for schizophrenia." (PMID 39036710, 2024).
schizophrenia (continued). "In participants with acute schizophrenia, TAAR1 agonists showed little difference compared to placebo in improving overall symptoms measured by PANSS total over a treatment of 4–6 weeks (number of studies N=4, number of participants n=1291, SMD=0.15, 95%CI: -0.05 to 0.34)." (PMID 39036710, 2024). "Two TAAR1 agonists, Ulotaront (Sunovion) and Ralmitaront (Hoffmann–La Roche), already advanced into clinical trials for the treatment of several conditions including narcolepsy, psychosis in Parkinson’s disease, and schizophrenia." (PMID 39110804, 2024). "The current preclinical evidence suggests that TAAR1 agonists may not only hold promise to improve schizophrenia symptoms, but potentially also comorbid metabolic dysfunction." (PMID 38237896, 2024). "TAAR1 agonists may be less efficacious than dopamine D2 receptor antagonists already licensed for schizophrenia." (PMID 39036710, 2024). "Emerging Phase 3 clinical data from this compound will not only be fundamental to our understanding of ulotaront but may help elucidate the therapeutic utility of TAAR1 agonists for the treatment of schizophrenia and beyond." (PMID 37165101, 2023). "In fact, the potential beneficial metabolic effects suggest that TAAR1 agonists may improve comorbid metabolic dysfunction in schizophrenia patients." (PMID 37165101, 2023). "Our study demonstrated the role of TAAR1 activation in schizophrenia treatment." (PMID 37153799, 2023). "Thus, 50B and SEP-856 had similar effects in reducing the distance traveled by mice, which suggests that TAAR1 activation is involved in how 50B counteracts the positive symptoms of schizophrenia." (PMID 37153799, 2023). "Discovering more TAAR1-activating drugs may aid the development of efficacious and safe treatments for schizophrenia." (PMID 37153799, 2023). "Therefore, the search for more novel activators of TAAR1 and related pharmacologic and pharmacogenetic studies are important for the development of therapeutic strategies for clinical schizophrenia." (PMID 37153799, 2023). "The discovery of a structurally novel TAAR1 agonist (50B) may provide valuable assistance in the development of new treatments for schizophrenia." (PMID 37153799, 2023). "Identified in 2001, Trace Amine-Associated Receptors (TAARs—six functional receptors found in humans: TAAR1, TAAR2, TAAR5, TAAR6, TAAR8, and TAAR9) comprise a family of G protein-coupled receptors that are clustered in a chromosomal region associated with schizophrenia." (PMID 37509616, 2023). "Overall, 50B, as a novel TAAR1 agonist, has good druggability, efficacy, and safety in schizophrenia treatment and may become a novel and powerful APD." (PMID 37153799, 2023). "In clinical trials, the first tested TAAR1 agonist with 5-HT1A agonist activity Ulotaront showed significant efficacy in treating patients with schizophrenia on both positive and negative symptoms without causing the side effects of existing antipsychotics." (PMID 35563838, 2022). "As TAAR1 might become a new target for schizophrenia since the discovery of D2 dopamine receptor blocking the action of antipsychotics more than 50 years ago, TAAR5 may emerge as a novel target for mood disorders." (PMID 35328548, 2022). "In a four-week phase 2 trial in patients with acute exacerbation of schizophrenia, the TAAR1 agonist, ulotaront, significantly improved PANSS total scores with respect to placebo control, with a generally favourable side effect profile (including a lack of metabolic effects)." (PMID 35393394, 2022). "TAAR1 agonists have already entered phase III clinical trials to treat schizophrenia." (PMID 35625001, 2022). "Trace amine-related receptor 1 (TAAR1) is a new type of target, and its agonists have been proven to be modulators of monoamine neurotransmitters, which are very effective in the treatment of schizophrenia." (PMID 35566106, 2022).
schizophrenia (continued). "Only recently, Phase 2 clinical study revealed the antipsychotic action of an agonist of novel molecular target for the treatment of schizophrenia—trace amine-associated receptor 1 (TAAR1)—that has no direct antagonistic action on D2 dopamine receptors." (PMID 36232878, 2022). "Ongoing Phase 2 and 3 clinical trials will determine whether TAAR1 agonists can circumvent the fate of prior, non-D2 receptor experimental drugs to become the first novel mechanism for the treatment of schizophrenia." (PMID 34947997, 2021). "Ulotaront, the first TAAR1 agonist to progress to randomized controlled clinical trials, has demonstrated efficacy in the treatment of schizophrenia, while another, ralmitaront, is currently being evaluated in clinical trials in schizophrenia." (PMID 34947997, 2021). "While TAAR1 partial and full agonists can differentially modulate baseline DA neuron firing, consistent antipsychotic-like effects of both partial and full agonists have been reported in several rodent models of schizophrenia." (PMID 34947997, 2021). "Mice lacking TAAR1 display higher VTA neuron firing rates and heightened behavioural sensitivity to psychostimulants, suggesting that pharmacological TAAR1 activation might be beneficial for tackling schizophrenia." (PMID 34445611, 2021). "Taken together, the current preclinical data suggest that TAAR1 agonists have the potential to improve several symptom domains of schizophrenia without causing adverse effects such as motor impairments or weight gain." (PMID 34947997, 2021). "Briefly, preclinical evidence indicates that TAAR1 agonists might be useful for the treatment of schizophrenia." (PMID 31643000, 2020). "Recent preclinical investigations have indicated that TAAR1 may play a pivotal role in a variety of psychiatric disorders, including schizophrenia, sleep disturbances, drug addiction, and stress-related disorders such as depression, bipolar disorder, and anxiety." (PMID 40351432, 2025). "Based on the preclinical studies, it might be expected that TAAR1 could be a potential drug target for several neuropsychiatric disorders, including schizophrenia, depression, bipolar disorder, generalized anxiety disorder, addiction, ADHD, Alzheimer’s disorder, etc.." (PMID 37509616, 2023). "50A and 50B, as novel TAAR1 agonists, may be efficacious and safe for schizophrenia treatment." (PMID 37153799, 2023). "Thus, the current preclinical evidence suggests that TAAR1 agonists hold promise to improve several symptom domains of schizophrenia without causing motor impairments and metabolic dysregulation." (PMID 37165101, 2023). "Additionally, a TAAR1 partial agonist (Ralmitaront), developed by Hoffmann-La Roche is currently under investigation in a Phase II clinical trial for the treatment of schizophrenia (ClinicalTrials.gov ID: NCT03669640) with another separate Phase II trial prematurely terminated (ID: NCT04512066)." (PMID 36100653, 2022). "Moreover, preclinical studies indicate that TAAR1 can modulate the activity of several neurotransmitter systems (such as dopamine, serotonin, and glutamate), which dysregulation is believed to be involved in the pathogenesis of schizophrenia." (PMID 36359001, 2022). "Thus, although TAAR1 agonists demonstrate antipsychotic-like efficacy in schizophrenia models, they are unlikely to cause extrapyramidal side effects (EPS, movement disorders), which are a well-known side effect of current antipsychotics." (PMID 34947997, 2021). "Under- or over-expression of TAAR1 may lead to schizophrenia, depression and addiction." (PMID 34946184, 2021). "In this section, we summarize preclinical evidence supporting TAAR1 agonists as a potential therapeutic candidate in schizophrenia that may offer differentiation from antipsychotics, which are limited to the efficacy and associated safety profile of D2 antagonism." (PMID 34947997, 2021).